INS (insulin)
Diseases named in the same sentence as INS in open-access papers (continued):
Sharing a sentence is not in itself a finding about the gene and the disease.
type 2 diabetes (continued). "The overall percentage of type 2 diabetes was 38.2%, and 12 of them were newly-diagnosed as type 2 diabetes after lung cancer; 45 patients took oral medication, while 21 patients subcutaneously injected insulin, and 15 patients took both oral medication and insulin as treatment for type 2 diabetes." (PMID 36615124, 2022). "Type 2 diabetes mellitus (T2DM) is a long-term metabolic illness defined by improper glucose metabolism and insulin resistance." (PMID 36291332, 2022). "Abnormal postprandial suppression of glucagon in Type 2 diabetes (T2DM) has been attributed to impaired insulin secretion." (PMID 35822422, 2022). "However, no inequalities on how the reform affected the risk of insulin initiation were found between income quintiles, implying co-payments unlikely are the most influential factor behind persisting inequalities in insulin initiation among individuals with type 2 diabetes in Finland." (PMID 36033350, 2022). "Combining a glucagon-like peptide-1 receptor agonist (GLP1-RA) with basal insulin is an emerging option when initiating injectable therapy in longstanding type 2 diabetes (T2DM)." (PMID 36244997, 2022). "Finger prick blood glucose (BG) monitoring remains a mainstay of management in people with type 2 diabetes (T2DM) who take sulphonylurea (SU) drugs or insulin." (PMID 34921531, 2022). "In addition, the morbidity of severe EPI was 12% (95% CI: 7%–19%, I2 = 86.17%) in type 2 diabetes patients with higher insulin requirement (1 group), which was significantly higher than that in patients with lower insulin requirement (2 group) (2%, 95% CI: 0%–13%, I2 = 86.58%)." (PMID 36213198, 2022). "In addition, as ER stress and insulin misfolding are well established in their roles in β cell dysfunction and demise in type 2 diabetes, IRE1α inhibition may well be considered for the treatment of type 2 disease." (PMID 34675883, 2021). "By contrast, in young adult-onset diabetes (DiYA), in individuals who were RBA-GADA positive, the addition of other IAbs was associated with increased frequency of early insulin treatment (21/42 [50%] vs 22/83 [26.5%], p = 0.01), but not in the older adult-onset diabetes (Action LADA)." (PMID 34272582, 2021). "The expression levels of glycine and carnosine were significantly up-regulated, leading to excessive oxidative stress, lipid oxidation, insulin resistance, and disruption of the TCA cycle, which may be associated with hyperlipidemia, aminophenemia, and type 2-diabetes." (PMID 34207667, 2021). "Therefore, protein supplementation could be advantageous for older women in order to preserve muscle mass, improve insulin action, and reduce the development and worsening of chronic diseases such as Type II diabetes." (PMID 34501915, 2021). "Type 2 diabetes mellitus (T2DM) is a progressive and complex metabolic disorder characterized by chronic hyperglycemia due to insulin resistance and pancreatic beta cell dysfunction." (PMID 34574899, 2021). "Type 2 diabetes mellitus (T2DM), which accounts for over 90% of diabetic patients, is mainly characterized by the dysfunction of pancreatic β-cells, resulting in defective insulin release and insulin resistance." (PMID 34685445, 2021). "Type 2 diabetes mellitus (T2DM) is a complex polygenic disorder characterised by the incapability of pancreatic β-ells to increase insulin secretion to compensate for insulin resistance (IR) in peripheral tissues." (PMID 34209638, 2021). "The serum follistatin level is increased in patients with NAFLD and type 2 diabetes, while individuals with reduced body weight after bariatric surgery exhibited a decrease in serum follistatin level, in conjunction with improved insulin sensitivity and glycemic control." (PMID 34944728, 2021). "A central feature of the etiology of type 2 diabetes mellitus (T2DM) is β‐cell failure, involving a deficit in insulin secretion and β‐cell apoptosis." (PMID 33769715, 2021).
type 2 diabetes (continued). "Our findings also provide compelling evidence in support of a previous hypothesis describing a shared pathomechanism between breast muscle myopathies in broilers and type 2 diabetes in mammals and suggest that potential alterations to pancreatic function and insulin action may be involved." (PMID 33762630, 2021). "Furthermore, the risk for type 2 diabetes is higher in women who have had gestational diabetes than in those who have not, due to defects in both insulin secretion and insulin action." (PMID 34657183, 2021). "This study demonstrated that GADA, whether detected by RBA or ECL assays, recognised a clinical phenotype distinct from type 2 diabetes in adult-onset diabetes patients, in that individuals were leaner, with a higher frequency of multiple autoantibodies and earlier need for insulin therapy." (PMID 34272582, 2021). "Another possibility is that the oscillations of glucose and insulin may be at different phases in LL compared to the behavioral rhythm, which may explain the lower glucose levels, as was seen in an example of a type 2 diabetic rodent model experiencing simulated jet-lag13." (PMID 35082987, 2021). "In type 1 diabetes (also known as insulin-dependent or childhood-onset), there is insulin production deficiency in the body, which requires daily administration of insulin, whereas in type 2 diabetes (known formally as non-insulin-dependent or adult-onset), the body cannot use insulin effectively." (PMID 34946438, 2021). "Furthermore, associations of fat cell size with comorbidities of obesity (Type 2 diabetes (T2D), dyslipidemia, and cardiovascular disease) have been reported and insulin-resistant individuals were found to exhibit larger visceral adipocytes compared to insulin-sensitive controls." (PMID 34172828, 2021). "Moreover, adipokines are also involved in the regulation of insulin signaling, and the imbalance of these factors may have an important role in the development of type 2 diabetes." (PMID 33919597, 2021). "Moreover, in obese patients with type 2 diabetes, sleep under hypoxic conditions imitating an altitude of 2400 m above sea level for 10 nights resulted in a reduction of fasting glucose and an improvement in insulin sensitivity." (PMID 34948667, 2021). "Insulin’s effects on oligodendrogenesis may have implications for disorders characterized by significant disruptions in insulin signaling, such as type 1 and type 2 diabetes." (PMID 33669242, 2021). "Thus, PBMT may improve insulin sensitivity of skeletal muscle through AMP/ATP-induced AMPK activation or ROS-induced PTEN/AKT activation in type 2 diabetes." (PMID 33795530, 2021). "The reduction in postprandial glycemia and insulinemia suggests that replacing regular wheat with RS2-enriched wheat may help prevent and potentially manage conditions such as type 2 diabetes by controlling rises in glucose and insulin following ingestion of carbohydrates." (PMID 33671147, 2021). "Indeed, decreased expression of exocytotic SNARE proteins in pancreatic islets is a postulated mechanism behind impaired insulin release, demonstrated by significantly reduced mRNA and protein levels in both rodent models of type 2 diabetes and islets of type 2 diabetic patients." (PMID 33937248, 2021). "It remains unknown whether BBR can improve DR in type I and type II diabetes with insulin therapy." (PMID 34803500, 2021). "Little is known about the comparative vascular safety of basal insulins (intermediate-acting human insulin [IAHI] or long-acting insulin analogue [LAIA]) in type 2 diabetes (T2D)." (PMID 33602950, 2021). "Moreover, insulin modulates BCAA transamination in type 2 diabetes and BCAT2 activity, suggesting that insulin resistance could lead to an accumulation of BCKAs due to defects in both BCAA transamination and oxidation." (PMID 34131782, 2021).
type 2 diabetes (continued). "Type 2 diabetes mellitus (T2DM) is a metabolic syndrome characterized by insulin dysfunction and abnormal glucose and lipid metabolism that has become one of the world’s most common public health problems." (PMID 33828910, 2021). "Sodium-glucose cotranspsorter-2 (SGLT2) inhibitors (SGLT2i) involve loss of skeletal muscle mass, potentially leading to inadequate HbA1c reduction in type 2 diabetes (T2DM), since muscle mass is related to insulin sensitivity." (PMID 34059720, 2021). "GPR40 agonists might be effective insulin secretagogues for treating type 2 diabetes." (PMID 34943862, 2021). "Type 2 diabetes mellitus (T2DM), a clinical chronic disease worldwide, has become an epidemic disease accompanying insulin resistance and insulin secretion defect." (PMID 33479232, 2021). "In the individuals with type 2 diabetes, a decrease in the measured insulin sensitivity was detected following MR blockade, during clamp stage 2, compared to before MR blockade (T2D: 153 ± 18 vs. 132 ± 24 ml h−1 prior vs. following intervention, p = 0.04)." (PMID 34350730, 2021). "In particular, higher albumin level, metformin, insulin, and sulfonylureas were the independently protective factors, but older age and CCI score≥3 were the independent risk factors for all-cause death in patients with pulmonary TB and type 2 diabetes comorbidity." (PMID 34513785, 2021). "The interplay between inflammation, immunity and metabolism has been outlined and, in this context, insulin signaling, similarly to what is observed in type 2 diabetes (T2D) or in metabolic syndrome, may be involved in the dysregulation of immune response in inflammatory diseases." (PMID 33995414, 2021). "Type 2 diabetes mellitus (T2DM), an expanding global health problem, is characterized by insulin resistance and impaired insulin secretion." (PMID 35095493, 2021). "SSB consumption has been related to increased blood insulin concentration, impaired fasting glucose (IFG), glucose intolerance (GI), insulin resistance (IR) and high risk of type 2 diabetes (T2D)." (PMID 35010944, 2021). "The objectives of this study were to examine the ability of machine learning models to predict insulin initiation by specialists and whether the machine learning approach could support decision making by general physicians for insulin initiation in patients with type 2 diabetes." (PMID 33502325, 2021). "Moreover, previous systematic reviews and meta‐analysis outlined significant effect of regular exercise in improving insulin sensitivity in patients with type 2 diabetes, but limited data are available in patients with overweight and obesity with or without type 2 diabetes." (PMID 33960110, 2021). "Astragalus polysaccharide was shown to enhance the glucose and lipid metabolism of type 2 diabetes mellitus (T2DM) rats by boosting insulin production through a protective impact on pancreatic islet beta cells." (PMID 34945554, 2021). "Metformin (N,N-dimethyl biguanide) is a first-line anti-hyperglycemic medication for the treatment of type 2 diabetes mellitus (T2DM), particularly in overweight or obese patients, by lowering the glucose levels and improving insulin sensitivity." (PMID 34638615, 2021). "Insulin sensitivity in the skeletal muscle and liver is a key target for interventions in type 2 diabetes (T2D)." (PMID 34940592, 2021). "Similarly, a decrease in the C‐peptide response was detected at the high dose of infused insulin, and a tendency during the low dose compared to baseline, in the individuals with type 2 diabetes, whereas a decrease occurred during both clamp stages in the healthy controls before MR blockade." (PMID 34350730, 2021). "Moreover, the result of a recent study that nucleotide reverse transcriptase inhibitors can improve insulin sensitivity and reduce the development of type 2 diabetes supports the relationship between the development of type II diabetes mellitus and CNVs extension as well." (PMID 33644055, 2021).
type 2 diabetes (continued). "ethanolic extract showed anti-type 2 diabetes (T2DM) activity via improving hyperglycemia, insulin sensitivity, and dyslipidemia." (PMID 33435282, 2021). "The same also has a more critical link to family history and lineage compared to Type I. Any mutations in proteins such as TCF7L2, ABCC8, GLUT2, and CAPN10 favor the progression of Type 2 diabetes because they could influence the production or mechanism of action of insulin." (PMID 34943006, 2021). "The effects of pharmacological androgen reduction or androgen receptor antagonists on insulin sensitivity have been less consistent; however, Mendelian randomization in a population-based study has supported a causal link between hyperandrogenemia and both PCOS and type 2 diabetes." (PMID 33901270, 2021). "In addition, osteoarthritis synovium from patients with type 2 diabetes showed insulin-resistant features, suggesting that type 2 diabetes may participate in joint catabolism." (PMID 34769215, 2021). "Furthermore, the genetic instruments for type 2 diabetes may be influenced by treatment, and genetic instruments for insulin explain a very low proportion of the variance in insulin concentrations." (PMID 33650017, 2021). "Accordingly, adiponectin levels decrease with obesity and type 2 diabetes mellitus (T2D) and correlate positively with insulin sensitivity and negatively with visceral adiposity." (PMID 33528828, 2021). "In addition, probiotics improve peripheral insulin sensitivity, thus, improving type 2 diabetes." (PMID 34574174, 2021). "GK rats are a non-obese Type 2 diabetes model of “isolated” β-cell dysfunction; many features resemble human disease including a loss of first phase insulin secretion, reduced β-cell mass, reduced islet insulin content, inflammation in islets, and impaired islet mitochondrial function." (PMID 33606677, 2021). "Type-2 diabetic patients eating a large 700 to 850 Kcal breakfast and a small 88 Kcal dinner experienced a 20% day-long decrease in blood glucose and 11 and 30%, respectively, increases in insulin, and GLP-1 concentrations compared to reversing the sizes of breakfast and dinner meals." (PMID 34959894, 2021). "In addition, nc886 methylation status associates with glucose and insulin levels during adolescence but not with the indicators of glucose metabolism or the incidence of type 2 diabetes in adulthood." (PMID 34294131, 2021). "This suggests that VAT inflammation and consequential disturbance of VAT insulin signaling could be critical events, which can start even before measurable increase of VAT mass, making it a silent risk factor for the development of type 2 diabetes." (PMID 34869524, 2021). "Moreover, several in vitro and animal studies show that glycosylated flavonoids may have a role in type 2 diabetes therapy by modulating hepatic glucose homeostasis and insulin sensitivity." (PMID 34946519, 2021). "We present a case of type 1 hypersensitivity to various preparations of insulin in a patient with insulin-dependent type 2 diabetes mellitus (T2DM)." (PMID 34325725, 2021). "In addition, age and family history of type 2 diabetes do not undermine the improvement in insulin sensitivity caused by exercise because exercise capacity occurs in parallel with improvement in muscle strength and body composition." (PMID 33562853, 2021). "In addition, although individuals receiving sulfonylurea therapy are likely to have type 2 diabetes, those who receive insulin only may include individuals with type 1 diabetes for whom insulin deintensification or discontinuation may be inappropriate." (PMID 34726745, 2021). "Interestingly, overnutrition (major risk factor of type 2 diabetes), oxidative stress or inhibition of SIRT3 (Class III histone deacetylases protein) lead to lysine hyperacetylation, mitochondrial dysfunction and to impair the insulin secretion process." (PMID 33844166, 2021).
type 2 diabetes (continued). "We recruited adults with type 2 diabetes who expressed an intention to fast during Ramaḍān and were adherent to one of four regimens—namely: metformin and glimepiride; metformin and vildagliptin; metformin and insulin glargine U100; or, metformin, insulin glargine U100, and human regular insulin." (PMID 34305809, 2021). "Worldwide prevalence of type 2 diabetes mellitus (T2DM) has reached 8.5% among adults, and it is characterized by elevated glucose concentrations and failing insulin secretion." (PMID 34249264, 2021). "Consequently, for the first time, it was proven that in type 2 diabetes insulin was inefficient rather than deficient." (PMID 33555509, 2021). "Today, there is no routinely and validated diagnostic methods to measure insulin sensitivity and, above all, there is no practical need to such a measurement, neither to predict type 2 diabetes nor to monitor the glycemic and metabolic control once the disease ensues." (PMID 33555509, 2021). "Type 2 diabetes mellitus (T2DM) is a metabolic disorder, characterized by hyperglycemia in the context of reduced insulin sensitivity and insulin resistance." (PMID 33750415, 2021). "The abnormal glucose increase with sufficient insulin levels in the blood is the typical characteristic of type 2 diabetes (T2D) in humans; however, the mechanisms are unclear." (PMID 33484713, 2021). "The intraventricular injection of FGF19 can increase phosphorylated AKT levels in the liver, quadriceps, and white adipose tissue, suggesting that FGF19 can enhance insulin sensitivity, indicating that it may represent a potential drug for the treatment of type 2 diabetes." (PMID 34307371, 2021). "Exercise improves insulin sensitivity and may contribute to the prevention of type 2 diabetes." (PMID 34042297, 2021). "Type 2 diabetes mellitus (T2DM) is a chronic metabolic disease characterized by progressive insulin resistance followed by deficit in insulin secretion." (PMID 34167557, 2021). "Adult-onset type 2 diabetes mellitus (T2DM) is defined as a chronic hyperglycemic state, characterized by insulin resistance and declining islet B-cell function, eventually leading to islet B-cell function failure." (PMID 34976508, 2021). "The evolutions are described of protocols and models for use in T1D, and Insulin-Requiring Type 2 Diabetes (T2D) that were the basis for studies in the Islet Recipients." (PMID 34335462, 2021). "Thus, GLP-1-based therapies, which were developed using insulin-inspired technologies and which originally were introduced to help people with type 2 diabetes, may also be valuable in type 1 diabetes." (PMID 35602193, 2021). "Type 2 diabetes mellitus (T2DM) accounted for more than 90% among diabetic patients, which is featured as insulin resistance in peripheral organs and insufficient insulin production by dysfunctional pancreatic β cells." (PMID 34485535, 2021). "Interestingly, each group of comparisons are all connected to the factors affecting the regulation of blood glucose, such as the Insulin signaling pathway, Insulin resistance, the Glucagon signaling pathway, Type II diabetes mellitus, and Type I diabetes mellitus." (PMID 32041309, 2020). "In this review, we present the advantages and adverse effects of SGLT2 inhibitors plus insulin therapy as a treatment regimen for patients with type 2 diabetes (T2D)." (PMID 32351447, 2020). "Furthermore, common polymorphisms within PTBP1 influence glucose-stimulated insulin secretion, albeit, in general, PTBP1 mRNA levels in the islets of individuals with impaired glucose tolerance and type 2 diabetes are unaffected as compared with individuals with normoglycaemia." (PMID 32894308, 2020). "Type 2 diabetes mellitus (T2DM) is a chronic metabolic disease characterised by peripheral insulin resistance (IR) and inadequate relative insulin secretion, resulting in hyperglycaemia." (PMID 32377863, 2020).